TFAP2C (transcription factor AP-2 gamma)
Description:
Sequence-specific DNA-binding transcription factor that interacts with cellular enhancer elements to regulate transcription of selected genes, and which plays a key role in early embryonic development. AP-2 factors bind to the consensus sequence 5'-GCCNNNGGC-3' and activate genes involved in a large spectrum of important biological functions. TFAP2C plays a key role in early embryonic development by regulating both inner cell mass (ICM) and trophectoderm differentiation (By similarity). At the 8-cell stage, during morula development, controls expression of cell-polarity genes (By similarity). Upon trophoblast commitment, binds to late trophectoderm genes in blastocysts together with CDX2, and later to extra-embryonic ectoderm genes together with SOX2 (By similarity). Binds to both closed and open chromatin with other transcription factors (By similarity). Involved in the MTA1-mediated epigenetic regulation of ESR1 expression in breast cancer.
Synonyms: AP2-gamma; ERF1; TFAP2G; hAP-2g
Tractability: PROTAC: UniProt records ubiquitination sites on it; ubiquitination databases record sites on it.
Gene: Protein-coding gene on chromosome 20 (56,629,306 to 56,639,283, forward strand). Ensembl gene ENSG00000087510.
Subcellular location: Nucleus
Subcellular location (Human Protein Atlas): Nucleoplasm
Pathways (Reactome):
Gene expression (Transcription): Activation of the TFAP2 (AP-2) family of transcription factors; Negative regulation of activity of TFAP2 (AP-2) family transcription factors; TFAP2 (AP-2) family regulates transcription of cell cycle factors; TFAP2 (AP-2) family regulates transcription of growth factors and their receptors; TFAP2 (AP-2) family regulates transcription of other transcription factors
Developmental Biology: Developmental Lineage of Mammary Stem Cells; Specification of the neural plate border
Metabolism of proteins: SUMOylation of transcription factors
Reproduction: Specification of primordial germ cells
Gene Ontology:
Molecular function: DNA binding; DNA-binding transcription activator activity, RNA polymerase II-specific; DNA-binding transcription repressor activity, RNA polymerase II-specific; protein binding; RNA polymerase II cis-regulatory region sequence-specific DNA binding; sequence-specific double-stranded DNA binding; DNA-binding transcription factor activity; DNA-binding transcription factor activity, RNA polymerase II-specific; RNA polymerase II transcription regulatory region sequence-specific DNA binding
Biological process: male gonad development; negative regulation of gene expression, epigenetic; positive regulation of transcription by RNA polymerase II; cell-cell signaling; morula formation; regulation of cell population proliferation; regulation of transcription by RNA polymerase II; inner cell mass cell differentiation; negative regulation of transcription by RNA polymerase II; regulation of DNA-templated transcription
Cellular component: nucleoplasm; nucleus; chromatin; cytosol
Genetic constraint (gnomAD): Loss-of-function variants: 8 observed, 34.6 expected, observed/expected ratio (o/e) 0.23, 90% interval 0.14 to 0.42. The upper end of that interval is the gene's LOEUF score, 0.42, which puts it in group 1 of 6, group 1 being the genes least tolerant of losing a copy. Missense variants: 440 observed, 523.28 expected, observed/expected ratio (o/e) 0.84, 90% interval 0.78 to 0.91. Synonymous variants: 250 observed, 223.66 expected, observed/expected ratio (o/e) 1.12, 90% interval 1.01 to 1.24.
Homologues: Orthologues: chimpanzee TFAP2C (100% identical), macaque TFAP2C (99% identical), dog TFAP2C (95% identical), pig TFAP2C (95% identical), rat Tfap2c (92% identical), rabbit TFAP2C (91% identical), guinea pig TFAP2C (89% identical), mouse Tfap2c (89% identical), tropical clawed frog tfap2c (69% identical), zebrafish tfap2c (66% identical), Drosophila melanogaster TfAP-2 (46% identical), Caenorhabditis elegans aptf-1 (34% identical), and 3 more. Paralogues in human: TFAP2A (64% identical), TFAP2B (60% identical), TFAP2E (54% identical), TFAP2D (48% identical).
Diseases named in the same sentence as TFAP2C in open-access papers:
TFAP2C is named in the same sentence as 63 diseases in open-access papers, as found by Europe PMC text mining. Sharing a sentence is not in itself a finding about the gene and the disease. The quoted sentences say what the papers report.
breast carcinoma (34 papers, 2011 to 2025). "TFAP2C is associated with unfavorable clinical outcomes and decreased response to anti-hormone therapy, such as tamoxifen and fulvestrant, in breast cancer." (PMID 37291585, 2023). "The loss of TFAP2C in luminal breast cancer cell lines induces luminal to basal transition accompanied by an increase in the expression of mesenchymal markers (Vimentin and N-cadherin) and loss of E-cadherin." (PMID 26905733, 2016). "In breast cancer, TFAP2C induces expression of ERα as well as other ERα-associated genes while represses expression of basal-associated gene, playing crucial role in maintaining the luminal phenotype of breast cancer." (PMID 38890750, 2024). "Furthermore, in breast cancer, the interaction between TFAP2C and metastasis-associated protein 1 (MTA1), a member of the nucleosome remodeling and HDAC complex, induces estrogen receptor (ER) expression via epigenetic chromatin modification." (PMID 37291585, 2023). "Loss of the TFAP2C transcription factor induced EMT in luminal breast cancers." (PMID 29383121, 2017). "Similarly transcription factor AP-2 gamma (TFAP2C), a transcription factor associated with estrogen receptor signaling in breast cancer, showed reduced expression in the mesenchymal state." (PMID 25538889, 2014). "TFAP2C may also be associated with breast cancer prognosis: higher TFAP2C levels correlate with poor overall survival in unique ERα(+) and endocrine therapy-treated subgroups, and high tissue TFAP2C expression also contributes to the failure of anti-hormone treatments." (PMID 29615098, 2018). "TFAP2C is indispensable for normal luminal cell development and retaining of luminal phenotypes in breast cancer." (PMID 37291585, 2023). "In breast cancer, alteration of SUMOylation on TFAP2A and TFAP2C demonstrates potential transformation between luminal and basal breast cancer phenotypes and concordant gene signatures." (PMID 37291585, 2023). "Tripartite motif-containing 37 (TRIM37) facilitates TFAP2C-mediated transcriptional activity on ERα in breast cancer." (PMID 37291585, 2023). "circ-ERBB2 acts as a ceRNA for miR-136-5p or miR-198 to relieve the repressive influence of miR-136-5p or miR-198 on TFAP2C in breast cancer." (PMID 37291585, 2023). "As summarized before, in breast cancer, TFAP2C regulates ER expression and plays an essential role in mediating the hormone response by regulating multiple pathways of ER-related signaling." (PMID 37291585, 2023). "In breast cancer, ER-related genes inversely induce TFAP2C expression by transcriptional activation and reliving chromatin conformation marked by high levels of histone H3 lysine 27 acetylation (H3K27Ac)." (PMID 37291585, 2023). "The enrichment of Tfap2c targets in mammary tumor and Maz targets in murine erythroleukemia cell suggesting that the CRM-associated genes represent biological-relevant targets of the CRM-binding TFs." (PMID 37841836, 2023). "A previous basic study showed that anlotinib inhibits the proliferation and induces apoptosis of MCF‐7 breast cancer cells by downregulating TFAP2C." (PMID 35965587, 2022). "In breast cancer, TFAP2C has multiple functions in regulating the expression of GPX4 in response to selenium supplementation." (PMID 35402284, 2022). "Meanwhile, our in-depth study clarified that both miR-136-5p and miR-198 negatively regulated the TFAP2C expression in HER2-Positive Breast Cancer cell lines, which was similar to the previous conclusions." (PMID 34732216, 2021). "TFAP2C interactions with PELP1 confer a growth advantage to breast cancer (BC) cells by activating an oncogenic RET signaling thus contributing to BC progression and therapy resistance." (PMID 33269540, 2021). "Circ-ERBB2 accelerated HER2-positive breast cancer progression through the circ-ERBB2/miR-136-5p/TFAP2C axis or the circ-ERBB2/miR-198/TFAP2C axis." (PMID 34732216, 2021).
breast carcinoma (continued). "In patients with HER2-positive breast cancer, the miR-136-5p or miR-198 was both negatively correlated with the TFAP2C expression." (PMID 34732216, 2021). "Conclusively, our data expounded that circ-ERBB2 was increased in tumor tissues of HER2-positive breast cancer patients and its expression was positively correlated with TFAP2C expression." (PMID 34732216, 2021). "With the continuous research on the TFAP2C function, increasing evidence expounds that TFAP2C mediates breast cancer progression." (PMID 34732216, 2021). "FREM2 has been identified as a target gene of TFAP2C (transcription factor AP-2 gamma) in hormone-responsive breast cancer cells." (PMID 32156290, 2020). "Knockdown of expression of transcription factor TFAP2C in hormone responsive breast carcinoma cells resulted in deregulation of a number of target genes including SLC24A3, which was downregulated." (PMID 31083655, 2019). "High expression of TFAP2C in breast cancer contributed to hormone resistance, which positively correlated with poor survival in breast cancer patients." (PMID 29439714, 2018). "TFAP2C has been reported to be upregulated in various types of cancer, including lung carcinoma, breast cancer, and high expression of TFAP2C significantly correlated with poor prognosis via promoting the growth and proliferation." (PMID 29439714, 2018). "Another study showed that through regulation of RET, the expression of TFAP2C decreased in luminal breast cancer." (PMID 30124166, 2018). "In breast cancer, TFAP2A functioned as a tumor suppressor; conversely, TFAP2C played an oncogenic role in the development and progression of breast cancer." (PMID 29439714, 2018). "In breast cancer, TFAP2C participates in regulating luminal-specific genes and is involved in multiple cell proliferation pathways, indicating that TFAP2C is a potential drug target site." (PMID 29615098, 2018). "The transcription factor activator protein 2C (TFAP2C) is very important in breast cancer biology, especially in luminal subtypes as it regulates genes including estrogen receptor-alpha (ERα) and HER2/c-erbB2." (PMID 26905733, 2016). "Some studies show that TFAP2C expression induces p21 mRNA and protein expression, leads to cell cycle arrest and inhibits the growth of human breast cancer cells." (PMID 24023917, 2013). "TFAP2C is reported to be upregulated in breast cancer, in squamous cell carcinoma (SCC), in germ cell tumors and ovarian cancer." (PMID 21779369, 2011). "In breast cancer TFAP2C transactivates the expression of HER-2/neu (ErbB2) and estrogen receptor genes." (PMID 21779369, 2011). "Several studies demonstrated a variety of target genes for TFAP2C in breast cancer tissue and cell lines." (PMID 21779369, 2011). "TFAP2C has been shown to regulate the cyclin-dependent kinase inhibitor (p21CIP1/CDKN1A) in breast cancer cell lines, but data are controversial." (PMID 21779369, 2011). "In addition, TFAP2C can transcriptionally stimulate RET expression independently of ER expression in breast carcinoma." (PMID 37291585, 2023). "Interestingly, TFAP2C has been considered to regulate luminal differentiation and its motif is enriched in luminal breast cancer cells." (PMID 32143622, 2020). "In breast cancer, transcription factor AP-2 gamma (TFAP2C) is an important transcription factor that regulates estrogen receptor-alpha (ERα) and c-ErbB2/HER2 (Her2), which are involved in the establishment of the gene expression pattern observed in different clinical phenotypes of breast cancer." (PMID 32571353, 2020). "Interestingly, TFAP2C is a key regulator of hormone responsiveness in breast carcinoma cells through the control of multiple estrogen signaling pathways." (PMID 32850739, 2020).
breast carcinoma (continued). "Recent studies on TFAP2C have mainly focused on breast cancer and lung cancer." (PMID 29615098, 2018). "Furthermore, TFAP2C has been extensively reported to be a poor prognostic marker in several human cancers, including breast cancer, lung carcinoma." (PMID 29439714, 2018). "The expression of TFAP2C is critical for maintaining the luminal phenotype of breast cancer cells." (PMID 26905733, 2016). "Similarly, TFAP2C transcriptionally activates p21 expression, retards breast cancer cell growth, and decreases clonogenic survival." (PMID 22348345, 2012). "In mammary cancer, TFAP2C expression results in increased progression of the tumors." (PMID 21779369, 2011). "Also it was suggested that the KLF14/miR-1283/TFAP2C axis inhibited HER2+ breast cancer progression, which might provide novel insight into mechanical exploration for this disease." (PMID 36831624, 2023). "Besides, EGFR and HER2 were regulated by TFAP2C in breast cancer." (PMID 30124166, 2018). "TFAP2C directly interacts with the EGFR gene to promote its expression, resulting in luminal breast cancer cell proliferation and an improved therapeutic effect of TKI (Vandetanib)." (PMID 37291585, 2023). "In detail, TFAP2C upregulates ER-related genes (ESR1, FOXA1 and GATA3) to maintain the phenotypes of luminal breast cancer." (PMID 37291585, 2023). "TFAP2C increases ERBB-related genes (EGFR, ERBB2, ERBB3), which mediate oncogenesis in ERBB2/HER2-amplified breast cancer." (PMID 37291585, 2023). "Transcription factor activator protein 2C (TFAP2C), also known as AP-2γ, mediates the breast cancer occurrence and is a promising marker for predicting the prognosis of patients with HER2-positive breast cancer." (PMID 34732216, 2021). "Meanwhile, in patients with HER2-positive breast cancer, we discovered a positive correlation between circ-ERBB2 and TFAP2C expressions." (PMID 34732216, 2021). "Mechanically, circ-ERBB2 positively regulated TFAP2C expression through sponging miR-136-5p or miR-198, thereby regulating HER2-positive breast cancer cell function." (PMID 34732216, 2021). "For example, TFAP2C regulates TGFBR2 transcription and promotes lung tumorigenesis and EMT, and TFAP2C regulation of CST1 transcriptional activation promotes breast cancer progression and inhibits iron death." (PMID 40995432, 2025). "Additionally, TFAP2C directly interacts with the EGFR gene to promote its expression, resulting in luminal breast cancer cell proliferation and an improved therapeutic effect of TKIs (Vandetanib)." (PMID 37291585, 2023). "Increased TFAP2C and reduced CD44 expression could be predictive of neoadjuvant chemotherapy in breast cancer." (PMID 37291585, 2023). "Mechanically, TFAP2A and TFAP2C are capable of binding the ERBB2 promoter, and in collaboration with other transcription factors, such as Ku protein and Yin Yang 1, they significantly promote ERBB2 expression in breast cancer cells." (PMID 37291585, 2023). "The expression levels of TFAP2A and TFAP2C are reduced post-translationally during TNFα-induced cell apoptosis, during which TFAP2A is cleaved by caspase 6 and degraded by the proteasome in the breast cancer cells." (PMID 37291585, 2023). "Generally, our data corroborated that circ-ERBB2 might act as an oncogene in HER2-positive breast cancer development and provide two novel regulatory axes for HER2-positive breast cancer: circ-ERBB2/miR-136-5p/TFAP2C and circ-ERBB2/miR-198/TFAP2C." (PMID 34732216, 2021). "Moreover, regulators such as TFAP2C, GTF2I and LMO4 were found to have potential prognostic value for lung metastasis free (LMF) survival of breast cancer." (PMID 31215771, 2019). "In contrast to TFAP2A, TFAP2C has been shown to be over-expressed, rather than lost in breast cancer cell lines and primary tumors." (PMID 24023917, 2013).
melanoma (18 papers, 2012 to 2025). A malignant, usually aggressive tumor composed of atypical, neoplastic melanocytes. "Since ECM1 levels appeared to have an inverse correlation with TFAP2A expression (in contrast to that observed in HMEC’s) and knowledge regarding the role of TFAP2C in melanomas is rather limited, we focused additional investigations on this association." (PMID 24023917, 2013). "Our investigations show an as yet unrecognized role for TFAP2C in melanoma via its regulation of ECM1." (PMID 24023917, 2013). "To summarize, our studies show that TFAP2C is an important player in the regulation of ECM1 expression in melanoma cells and that its effect is mediated by direct interaction with the ECM1 promoter." (PMID 24023917, 2013). "While TFAP2A has been extensively studied in melanoma, our investigations show an as yet unrecognized and understudied role for TFAP2C in this malignancy via its regulation of ECM1 expression." (PMID 24023917, 2013). "Expression of miR-214 in melanoma cells promotes TFAP2C-mediated metastasis, mainly by promoting trans-endothelial migration, but also by suppressing anoikis resistance." (PMID 23185507, 2012). "Studies have also reported that miR-214 contributes to the progression and metastasis of melanoma through the suppression of TFAP2C." (PMID 22962603, 2012). "Indeed, AP-2 family members such as TFAP2A, TFAP2B, and TFAP2C have been shown to be involved in different cancer types such as glioblastoma, melanoma, acute myeloid leukemia, pancreatic cancer, and colorectal cancer." (PMID 39013578, 2024). "However, other studies have shown that TFAP2C played a tumor suppressive role in several human cancers, such as melanoma, endometrial cancer." (PMID 29439714, 2018). "In contrast to TFAP2A, there is very limited data regarding the role of TFAP2C in melanoma." (PMID 24023917, 2013). "MiR-214 could contribute to melanoma tumour progression through suppression of TFAP2C." (PMID 24465927, 2014). "Along the other branch, we observed upregulation of the NFI transcription factors, and less well-studied transcription factors in melanoma biology such as TFAP2B and TFAP2C (AP2 transcription factors)." (PMID 38183207, 2025). "TFAP2A and TFAP2C are members of the TFAP2 transcription factor family, which plays a crucial role in regulating melanocyte differentiation and melanoma phenotypes." (PMID 40725490, 2025). "To test this model in SK-MEL-28 melanoma cells we deleted the two TFAP2 paralogs with highest expression, TFAP2A and TFAP2C, creating TFAP2 knockout (TFAP2-KO) cells." (PMID 35580127, 2022). "Luciferase and expression assays in human melanoma samples confirmed that miR-214 targets the adhesion molecule integrin α3 (ITGA3) and transcription factor AP-2 gamma (TFAP2C)." (PMID 34943783, 2021). "In this study, we found that ECM1 is over-expressed in several melanoma cell lines, when compared to primary melanocytes, and furthermore, that ECM1 expression paralleled that of TFAP2C levels in multiple cell lines." (PMID 24023917, 2013). "Several miR-214 targets have been characterized in various tumor types (ovarian cancer, cervical cancer and melanoma) including MEK3, JNK1, PTEN, Plexin-B1, Ezh2, and TFAP2C and so on." (PMID 22359598, 2012). "However, NFATC2 and TFAP2C, key markers of the AP2 invasive state identified in the Tirosh data, were broadly expressed throughout the Rambow melanoma cells." (PMID 38183207, 2025). "LASSO regression analysis was used to filter TFs further in order to identify a biomarker that could predict the prognosis of patients with melanoma, based on which seven TFs (TBX21, MYB, GFI1, NFE2L3, TFAP2C, HEY2, NR2F2) were selected." (PMID 37435067, 2023). "Thus, early requirements for Tfap2a and its paralog Tfap2c observed in zebrafish neural crest induction may suggest a role for TFAP2 in this invasive subtype of melanoma as well." (PMID 28249010, 2017).